DGCR5 (DiGeorge syndrome critical region gene 5)
Diseases named in the same sentence as DGCR5 in open-access papers (continued):
Sharing a sentence is not in itself a finding about the gene and the disease.
non-small cell lung carcinoma (3 papers, 2019 to 2025). A group of at least three distinct histological types of lung cancer, including non-small cell squamous cell carcinoma, adenocarcinoma, and large cell carcinoma. "DGCR5 acts as a key regulator of CSCs in non-small-cell carcinoma by modulating the miR-330-5p/CD44 axis." (PMID 41008534, 2025). "DGCR5 was upregulated in lung adenocarcinoma tissues and promoted cancer progression through inhibiting miR-22-3p, and the same team concluded that DGCR5 contributed to the cancer stem cell–like properties in non-small cell lung cancer through interacting with miR-330-5p/CD44." (PMID 34322486, 2021). "Coincidentally, the lncRNAs plasmacytoma variant translocation 1 (PVT1), diGeorge syndrome critical region gene 5 (DGCR5), and cytoskeleton regulator RNA (CYTOR) were confirmed to decrease the radiosensitivity of non-small cell lung cancer cells by sponging miR-195." (PMID 31391206, 2019).
pancreatic ductal adenocarcinoma (3 papers, 2017 to 2019). An infiltrating adenocarcinoma that arises from the epithelial cells of the pancreas. "The lncRNA DGCR5 and miR-320a regulate each other in a reciprocal manner, and DGCR5 could reverse the inhibition of PDCD4 by miR-320a, which is involved in the regulation of the pancreatic ductal adenocarcinoma cell phenotype." (PMID 31620370, 2019).
bladder cancer (2 papers, 2021). "LncRNA DiGeorge syndrome critical region gene 5 (DGCR5) is significantly downregulated in bladder cancer." (PMID 34422802, 2021). "Overexpression of DGCR5 represses cell proliferation, cell cycle progression, migration, invasion, and EMT while promotes cell apoptosis of bladder cancer." (PMID 34422802, 2021).
breast carcinoma (2 papers, 2020 to 2022). "For the TNBC subtype, although understanding of the identified subtype-specific genes is less than other two types, the roles of DGCR5, RAD51L1, and TTLL4 in breast cancer are well studied." (PMID 35646077, 2022).
cervical cancer (2 papers, 2021). A primary or metastatic malignant neoplasm involving the cervix. "Downregulation of DGCR5 contributed to cervical cancer progression by activating Wnt signalling." (PMID 34093798, 2021).
DiGeorge syndrome (2 papers, 2021 to 2023). "DGCR5, DGCR9, and PRODH in 22q11.21 have been reported to be associated with Digeorge Syndrome." (PMID 34079576, 2021).
hyperprolinemia type 1 (2 papers, 2016 to 2021). Hyperprolinaemia type I is an inborn error of proline metabolism characterized by elevated levels of proline in the plasma and urine. "A recent case control study reported microdeletions encompassing the PRODH and DGCR6 genes to be a strong risk factor for hyperprolinemia type 1 but not for autism spectrum disorder suggesting more emphasis on the other lesser known FAM230F and DGCR5 genes." (PMID 34938854, 2021).
lung adenocarcinoma (2 papers, 2021). A carcinoma that arises from the lung and is characterized by the presence of malignant glandular epithelial cells. "In previous reports, hsa-miR-22-3p was inhibited by lncRNA DGCR5 to promote the progression of lung adenocarcinoma." (PMID 34825062, 2021).
papillary thyroid carcinoma (2 papers, 2020 to 2021). "For example, lncRNA DGCR5 acts as a tumor suppressor in papillary thyroid carcinoma via targeting miR-2861." (PMID 32770994, 2020).
Parkinson disease (2 papers, 2015 to 2017). A progressive degenerative disorder of the central nervous system characterized by loss of dopamine producing neurons in the substantia nigra and the presence of Lewy bodies in the substantia nigra and locus coeruleus. "There were only two enriched pathways associated with the DGCR5-coexpressed genes: glycolysis and Parkinson's disease." (PMID 27903974, 2017).
prostate carcinoma (2 papers, 2021). A carcinoma that arises from epithelial cells of the prostate gland. "Similarly, DGCR5, is located in the DiGeorge critical locus and has been linked to neurodevelopment and neurodegeneration, and was recently implicated as a tumour suppressor in prostate cancer." (PMID 34316704, 2021). "However, our results show that the expression of DGCR5 is remarkably higher in ccRCC than in gastric, lung, liver, colon, and prostate cancer." (PMID 34322486, 2021).
astrocytoma (1 paper, 2020). "According to REMBRANDT data, lncRNA DGCR5 expression was dramatically downregulated in oligodendroglioma, astrocytoma, and glioblastoma, compared with normal (noncancerous) tissues." (PMID 33085646, 2020). "According to GSE4290, lncRNA DGCR5 expression showed to be remarkably downregulated within oligodendroglioma, astrocytoma, and glioblastoma, in comparison with that in normal (non-cancerous) tissues." (PMID 33085646, 2020).
clear cell renal cell carcinoma (1 paper, 2021). "We identified DiGeorge Syndrome Critical Region Gene 5 (DGCR5) as a clear cell renal cell carcinoma (ccRCC) cancer- and lineage-specific lncRNA." (PMID 34322486, 2021).
triple-negative breast carcinoma (1 paper, 2022). An invasive breast carcinoma which is negative for expression of estrogen receptor (ER), progesterone receptor (PR), and human epidermal growth factor receptor 2 (HER2). "Moreover, DGCR5, having the third highest score under our prediction, reportedly incudes tumorigenesis of triple-negative breast cancer by affecting the Wnt/β-catenin signaling pathway." (PMID 35646077, 2022).
tumor (29 papers, 2017 to 2025). "DGCR5 has been specifically implicated in the tumor progression of LUAD through the inhibition of hsa-mir-22-3p." (PMID 36551790, 2022). "GSEA analysis inferred the potential translational silencing effect of DGCR5 on oncogenic target proteins via binding with a miRNA target in the canonical lncRNA–miRNA–mRNA signalling axis, which supports its tumour-suppressive role." (PMID 37372103, 2023). "SMAD7 as a Tumor Suppressor: Positive regulation of SMAD7 by LncRNAs: NFκB1 transcriptionally downregulated DGCR5 in glioma cells." (PMID 33511320, 2021). "Knockdown of DGCR5 inhibited the proliferation, migration and invasion by inducing cell apoptosis and G0/G1 cell cycle arrest of PC cells in vitro, and suppressed PC tumor growth in vivo." (PMID 33613108, 2021). "We investigate the biological functions of DGCR5 isoform-1 in ccRCC and show that DGCR5 isoform-1 exerts a tumor-promoting effect in ccRCC." (PMID 34322486, 2021). "DGCR5 overexpression considerably reduced the tumor volumes and weights of SHG44-derived and U251-MG-derived tumors." (PMID 33511320, 2021). "miR-23a negatively regulated PTEN and enhanced tumor progression but DGCR5 interfered with miR-23a-mediated inhibition of PTEN." (PMID 33511320, 2021). "RNA Fluorescence in situ hybridization (FISH) analysis in PC tumor tissues and cell lines displayed that DGCR5 was primarily located in the cytoplasm." (PMID 33613108, 2021). "We found that tumor volumes and weights in silencing the DGCR5 group were significantly suppressed compared with the control." (PMID 34099633, 2021). "RNA FISH assay using xenograft tumor tissues further demonstrated that DGCR5 mainly located in the cytoplasm." (PMID 33613108, 2021). "The results indicated that DGCR5 expression was notably incresed in PC tissues compare with non-tumor tissues." (PMID 33613108, 2021). "LncRNA DGCR5 overexpression significantly reduced the tumor volume and weight of both U251-MG-derived and SHG44-derived tumors." (PMID 33085646, 2020). "In the same vein, our results showed that CCT137690 treatment upregulates expression lncRNA DGCR5, as a potential tumor suppressor, in MCF-7 cells." (PMID 31319040, 2020). "In summary, lncRNA DGCR5 acts as a tumor suppressor through the DGCR5/miR-21/Smad7 and DGCR5/miR-23a/PTEN axes." (PMID 33085646, 2020). "We examined the effects of lncRNA DGCR5 on tumor growth, proliferation markers, cell cycle regulators, and EMT markers." (PMID 33085646, 2020). "LncRNA DGCR5 exerted its tumor-suppressive effects through the DGCR5/miR-21/Smad7 and DGCR5/miR-23a/PTEN axes." (PMID 33085646, 2020). "Collectively, these data demonstrated that DGCR5 acts as a ceRNA of miR-3619-5p and inhibited the tumor suppressive effects of miR-3619-5p in GBC." (PMID 32742494, 2020). "Mechanistically, DGCR5 functions as a competing endogenous RNA (ceRNA) by competitively binding to tumor suppressor miR-3619-5p via activating MEK/ERK and JNK/p38 MAPK signaling pathways." (PMID 32742494, 2020). "The results showed that DGCR5 expression was higher in GBC tissues compared to adjacent non-tumor tissues, and also higher in GBC cell lines (NOZ, SGC-996, GBC-SE and OCUG) than 293T cells." (PMID 32742494, 2020). "On the other hand, tumor suppressor lncRNAs (e.g., DGCR5 and IGF2AS) were upregulated in the ER-positive cell line." (PMID 31319040, 2020). "Further investigation demonstrated that DGCR5 promotes the sensitivity of PDAC cells to 5-FU, which indicates a tumor suppressive role for DGCR5 in PDAC." (PMID 29207609, 2017). "We found that DGCR5 is significantly reduced in clinical PDAC samples and PDAC cell lines and that a downregulated DGCR5 level is associated with tumor-free survival and the malignant phenotype of PDAC cells." (PMID 29207609, 2017). "From our clinical database analysis, DGCR5 is one of the downregulated lncRNAs, which may suggest its tumour-suppressive role." (PMID 37372103, 2023).
tumor (continued). "Furthermore, overexpression of DGCR5 significantly increased the level of the epithelial marker E-cadherin in tumor tissues." (PMID 33511320, 2021). "The tumor-promoting or -suppressive role of DGCR5 during carcinogenesis is not clearly understood." (PMID 34322486, 2021). "DGCR5 is highly selectively expressed in ccRCC tissues, and at the same time, its expression level in ccRCC is quite high, which is one of the main reasons that we decided to further investigate its clinical use as a tumor biomarker." (PMID 34322486, 2021). "For instance, DGCR5 played as a tumor suppressor in TC though binding to miR-2861." (PMID 32377223, 2020). "For example, since the smaller tumor size is connecting to DGCR5 down-regulation." (PMID 33372601, 2020). "LncRNA DGCR5 acts as a tumor-suppressor lncRNA in a variety of cancers." (PMID 33085646, 2020). "Regarding the underlying molecular mechanisms, lncRNA DGCR5 could inhibit miR-21 and miR-23a expression, and miR-21 or miR-23a overexpression significantly reversed the tumor-suppressive effects of lncRNA DGCR5 overexpression." (PMID 33085646, 2020). "Regarding the underlying molecular mechanisms, lncRNA DGCR5 could target to inhibit miR-21 and miR-23a expression, and miR-21 or miR-23a overexpression significantly reversed the tumor-suppressive effects of lncRNA DGCR5 overexpression." (PMID 33085646, 2020). "The role of DGCR5 in tumorigenesis in vivo was consistent with in vitro assays, Ki‐67‐positive cell number (exhibited by immunohistochemical staining), tumor size, and tumor weight of A549‐DGCR5 group were significantly lower in comparison with A549‐control group." (PMID 29790668, 2018). "Moreover, xenograft assay validated that DGCR5 promotes PC tumor growth in vivo." (PMID 33613108, 2021). "Taken together, these results suggested that DGCR5 might be a tumor suppressor in LC." (PMID 29790668, 2018). "On the other hand, LINC01111, LINC01963, DGCR5, MEG3, GAS5, and LINC00261 are among tumor suppressor lncRNAs in this tissue." (PMID 34827663, 2021). "To study the molecular mechanisms of DGCR5-mediated tumor-promoting effects in human RCC, we analyzed potential miRNA targets of DGCR5 using the miRcode database and DIANA-LncBase v2." (PMID 34322486, 2021). "Some of the top DNA hypermethylated IRGs, such as BMP8B, PLA2R1, MSX1, DGCR5, and MT1G, were previously identified as tumor suppressors in gastric and other cancers." (PMID 32841292, 2020). "We found that DGCR5 was significantly overexpressed and acted as an oncogene in GBC, in contrast, miR-3619-5p was downregulated and acted as a tumor suppressor in GBC." (PMID 32742494, 2020). "Thus, we hypothesized that DGCR5 exerts its tumor-suppressive effects through miR-21/miR-23a." (PMID 33085646, 2020). "Mechanistically, DGCR5 inhibits GBC cell proliferation, migration, invasion and tumor growth via sponging miR-3619-5p and activating MEK/ERK1/2 and JNK/p38 MAPK pathways." (PMID 32742494, 2020). "DGCR5 knockdown inhibited the GBC cell proliferation, migration, invasion, induced apoptosis, cell cycle arrest in vitro, and suppressed GBC tumor growth in vivo." (PMID 32742494, 2020). "IGF2BP2-AS1 and DGCR5 upregulation and amplification predicted better LUSC prognosis, possibly functioning as tumor suppressors." (PMID 27903974, 2017). "For example, lncRNA DGCR5 reduced the expression of hsa-mir-22-3p and promoted LUAD tumor growth." (PMID 35711823, 2022). "Moreover, DGCR5 also lead to significant expression in migration and invasion‐related marker MMP‐3 and MMP‐9 in tumor samples." (PMID 29790668, 2018). "Moreover, DGCR5 overexpression significantly decreased the protein levels of proliferation marker ki-67, cell cycle regulator Cyclin D1, and mesenchymal marker TWIST, but increased the protein level of the epithelial marker E-cadherin in tumor tissues." (PMID 33085646, 2020).
cancer (18 papers, 2017 to 2023). A tumor composed of atypical neoplastic, often pleomorphic cells that invade other tissues. "Long noncoding RNA DiGeorge syndrome critical region gene 5 (DGCR5) has been shown to be highly associated with cancer development." (PMID 33613108, 2021). "Since metastasis is the component of cancer that causes death, we investigated the role of DGCR5 in the migration and invasiveness of PDAC cells by a Transwell migration and invasion assay." (PMID 29207609, 2017). "A growing body of evidence shows that DGCR5 is highly associated with cancer development 18-20." (PMID 33613108, 2021). "To determine the biological role of DGCR5 in PC, we measured its expression in 38 pairs of PC tissues and adjacent non-cancer tissues by qRT-PCR." (PMID 33613108, 2021). "Our previous data mining and analysis of publicly available RNA sequencing data identified DiGeorge Syndrome Critical Region Gene 5 (DGCR5) as a ccRCC cancer- and lineage-specific expressed lncRNA, which highly expresses in ccRCC human tissues." (PMID 34322486, 2021). "Amounting evidence has been shown that lncRNA DGCR5 is involved in various cancers, however, the effect of DGCR5 in the tumorigenesis still remains controversial." (PMID 32742494, 2020). "LncRNA DiGeorge syndrome critical region gene 5 (DGCR5) plays cancer-dependent roles." (PMID 36819921, 2023). "Long noncoding RNA (lncRNA) DiGeorge syndrome critical region gene (DGCR5) has been reported to participate in various types of cancers, but its role in GBC remains largely unknown." (PMID 32742494, 2020). "Increasing data has displayed that DGCR5 is highly involved in many cancers 14-16." (PMID 32742494, 2020). "DGCR5 is a DiGeorge syndrome-related gene, and its role in cancers is currently uncertain." (PMID 27903974, 2017). "DGCR5 is strongly related to stem cell properties, both for promoting differentiation and inducing stem cell-like status, which could influence positively or negatively cancer initiation and progression." (PMID 35205253, 2022). "The lncRNA DiGeorge syndrome critical region gene 5 (DGCR5) was downregulated in HCC tissues and serum, which correlated closely with poor cancer-specific survival, with an overall 5-year rate of 10.3% in the low expression group and 36.6% in the high expression group, respectively." (PMID 34638971, 2021).
DGCR5 also shares sentences with these, for which no sentence is quoted: gallbladder cancer (2 papers); liver cancer (2); autism spectrum disorder (1); colon cancer (1); colorectal cancer (1); developmental delay (1); esophageal cancer (1); glioblastoma (1); larynx squamous cell carcinoma (1); liver diseases (1); melanoma (1); oligodendroglioma (1); osteosarcoma (1); ovarian carcinoma (1); postmenopausal osteoporosis (1).